IQGAP3 (IQ motif containing GTPase activating protein 3)
Tractability: Small molecule: it has a binding pocket of medium quality. PROTAC: ubiquitination databases record sites on it.
Gene: Protein-coding gene on chromosome 1 (156,525,405 to 156,572,604, reverse strand). Ensembl gene ENSG00000183856.
Subcellular location (Human Protein Atlas): Nucleoli rim; Mitotic chromosome; Nucleoplasm
Pathways (Reactome):
Signal Transduction: CDC42 GTPase cycle; RAC1 GTPase cycle; RHO GTPases activate IQGAPs; RHOA GTPase cycle; RHOB GTPase cycle; RHOC GTPase cycle; RHOJ GTPase cycle; RHOQ GTPase cycle
Gene Ontology:
Molecular function: calmodulin binding; myosin VI light chain binding; protein binding; actin filament binding; GTPase activator activity; small GTPase binding
Biological process: mitotic actomyosin contractile ring assembly actin filament organization
Cellular component: cell cortex; cytosol; cell-cell junction; cytoplasm; lateral plasma membrane
Genetic constraint (gnomAD): Loss-of-function variants: 157 observed, 203.28 expected, observed/expected ratio (o/e) 0.77, 90% interval 0.68 to 0.88. The synonymous counts are far from expectation, so gnomAD's model fits this gene poorly and the ratio says little. Missense variants: 1,780 observed, 2,082.1 expected, observed/expected ratio (o/e) 0.85, 90% interval 0.82 to 0.89. Synonymous variants: 697 observed, 825.91 expected, observed/expected ratio (o/e) 0.84, 90% interval 0.79 to 0.9.
Homologues: Orthologues: macaque IQGAP3 (97% identical), chimpanzee IQGAP3 (97% identical), pig IQGAP3 (92% identical), rabbit IQGAP3 (91% identical), guinea pig IQGAP3 (88% identical), dog IQGAP3 (86% identical), rat Iqgap3 (86% identical), mouse Iqgap3 (85% identical), tropical clawed frog iqgap3 (67% identical), zebrafish iqgap3 (59% identical), Caenorhabditis elegans pes-7 (23% identical). Paralogues in human: IQGAP1 (59% identical), IQGAP2 (50% identical).
Diseases named in the same sentence as IQGAP3 in open-access papers:
IQGAP3 is named in the same sentence as 60 diseases in open-access papers, as found by Europe PMC text mining. Sharing a sentence is not in itself a finding about the gene and the disease. The quoted sentences say what the papers report.
bladder cancer (17 papers, 2014 to 2025). "Currently, most studies have indicated that IQGAP3 functions as a promoter of tumorigenesis and is associated with a poor prognosis in various tumor types, including hepatocellular cancer, bladder cancer, lung cancer, and breast cancer." (PMID 41446602, 2025). "ROC curve analysis revealed that IQGAP3 is a highly sensitive and specific diagnostic marker for bladder cancer, which can reach 80.0% and 83.8%, respectively." (PMID 36831467, 2023). "IQGAP3 was also overexpressed in bladder cancer tissues, and can promote bladder cancer progression via activating the Ras/ERK pathway." (PMID 36831467, 2023). "IQGAP3 expression was increased in the cancer of the bladder, breast, colorectum, stomach, kidney, liver, and lung." (PMID 35274003, 2022). "High expression of IQGAP3 has been observed in colorectal cancer, hepatocellular carcinoma, bladder cancer, and gastric cancer." (PMID 35274003, 2022). "Previous studies suggested that IQGAP3 was overexpressed at mRNA level in multiple cancer tissues, including bladder cancer." (PMID 33672869, 2021). "Growing evidence suggests IQGAP3 is overexpressed in various tumors, including melanoma, pancreatic cancer, gastric cancer, bladder cancer, hepatocellular carcinoma, and breast cancer." (PMID 33519444, 2020). "For IQGAP3, all 16 analyses, including bladder cancer, breast cancer, colorectal cancer, esophaseal cancer, liver cancer and lung cancer, showed significantly higher mRNA expression in cancer tissues, compared to normal tissue." (PMID 29073199, 2017). "Expression levels of IQGAP3 in tissue and urine samples from bladder cancer patients are significantly higher than those in samples from control groups, and IQGAP3 was upregulated by CDC42 activation of the Ras/ERK pathway, promoting the development of bladder cancer." (PMID 36362301, 2022). "Growing evidence suggests that IQGAP3 is a biogenetic or prognostic marker of malignancy that promotes migration, invasion, and drug resistance in many human malignancies, such as gastric cancer, clear cell renal cell carcinoma, bladder cancer, and liver cancer." (PMID 38560572, 2024). "IQGAP3 has been shown to be upregulated in breast cancer, pancreatic cancer, gastric cancer, hepatocellular carcinoma, colorectal cancer and bladder cancer, and is closely related to clinicopathological features, suggesting that it may be involved in tumor development." (PMID 36275458, 2022). "In a study involving 355 bladder cancer patients and non-malignant hematuria patients, urine PCR detection of IQGAP3/BMP4 and IQGAP3/FAM107A showed a sensitivity of 71.0%, specificity of 88.6%, and an area under the curve (AUC) of 0.862." (PMID 40191434, 2025). "Furthermore, IQGAP3 can distinguish myoinvasive bladder cancer (MIBC) from non-myoinvasive bladder cancer (NMIBC), achieving sensitivity and specificity maxima of 93.8% and 80.0% for MIBC and 89.5% and 90.7% for NMIBC with PicoGreen-corrected AUCs of 0.944 and 0.87, respectively." (PMID 39295845, 2024). "While IQGAP3 expression in normal tissues was restricted to the colon, small intestine and testis, high levels of IQGAP3 mRNA were observed in a number of tumors including lung cancer, hepatocellular carcinoma, renal cancer, gastric cancer, bladder cancer, colon cancer and leukemia (data not shown)." (PMID 24849319, 2014). "In a cohort of 355 patients with either bladder cancer or non-malignant hematuria, IQGAP3/BMP4 and IQGAP3/FAM107A urine PCR ratios yielded a sensitivity of 71.0%, specificity of 88.6%, and AUC of 0.862." (PMID 38927984, 2024).
lung carcinoma (16 papers, 2014 to 2025). "First, the expression of IQGAP3 alsoincreased in lung cancer tissue and associated with poor prognosis." (PMID 29581849, 2018). "In summary, our studies reveal for the first time the involvement of IQGAP3 in lung cancer development and the potential molecular mechanisms underlying its tumor-promoting activity." (PMID 24849319, 2014). "Moreover, suppression of IQGAP3 in a lung cancer cell line caused a reduction in the tumorigenicity of these cells in lung tissue after intravenous injection." (PMID 24849319, 2014). "It would be interesting to determine whether 1q21.3 amplification contributes to the upregulation of IQGAP3 which is found in lung cancer, and whether 1q21.3 amplification observed in gastroesophageal carcinomas or breast cancer is associated with increased IQGAP3 expression." (PMID 24849319, 2014). "Our study demonstrates the multifaceted roles of IFFO1 in lung cancer by modulating the IQGAP3-Cdc42 axis and suggests the potential for identifying tumor targets through the examination of intermediate filament networks and their associated co-factors." (PMID 40634295, 2025). "In lung cancer, this is accomplished through IQGAP3's regulation of EGFR-ERK signaling, whereas in hepatocellular carcinoma, this is accomplished by promoting TGF-β, which is a key EMT regulator." (PMID 35355828, 2022). "In lung cancer, IQGAP3 directly bind repair protein Rad17 to regulate its expression and localization at the DNA damage site, so as to promote DNA repair." (PMID 36275458, 2022). "In lung cancer, the interaction of IQGAP3 with DNA repair protein Rad17 was essential for Rad17 expression and foci formation, the Mre11-Nbs1-Rad50 complex formation, and ATM/Chk2 and ATR/Chk1 pathways activation." (PMID 36275458, 2022). "Particularly, a high expression level of IQGAP3 was observed in metastatic samples of lung cancer, which was identified as a marker of poor prognosis." (PMID 32824461, 2020). "Two studies showed that IQGAP3 promoted the growth and metastasis of lung cancer cells by modulating EGFR-ERK signaling." (PMID 32824461, 2020). "For example, enforced expression of IQGAP3 accelerated the migration and invasion of lung cancer cells by interacting with ERK1 and promoting EGF-induced activation of ERK." (PMID 28810875, 2017). "Oncomine analysis of cancer vs. normal tissue in different datasets showed altered expression of IQGAP2 and IQGAP3 in different subtypes of lung cancer." (PMID 29073199, 2017). "In the current study, we provide the first evidence that IQGAP3 promotes lung cancer growth and metastasis by enhancing EGFR-mediated ERK signaling." (PMID 24849319, 2014). "Here we demonstrate IQGAP3 expression is markedly increased in lung cancer tissues at both mRNA and protein levels." (PMID 24849319, 2014). "Using this model, knockdown of IQGAP3 in lung cancer cells was found to greatly impair its capacity to generate metastatic lesions in the lung." (PMID 24849319, 2014). "Although in our study, we demonstrate that upreguation of IQGAP3 is a common event in lung cancer, we should mention that there are a few lung cancer samples which show unchanged or even decreased expression of IQGAP3." (PMID 24849319, 2014). "We next examined IQGAP3 protein expression in a tissue array containing 89 paired lung cancer tissues." (PMID 24849319, 2014). "We conducted a comprehensive assessment of the function of IQGAP3 in lung cancer cells." (PMID 40634295, 2025). "Finally, we undertook real-time reverse transcription-quantitative polymerase chain reaction (RT-qPCR) and immunohistochemistry (IHC) assays to show that IQGAP3 had high expression in non–small-cell lung cancer (NSCLC) cell lines and cancer tissue." (PMID 35274003, 2022). "In addition, knockdown of IQGAP3 by siRNA in A549 lung cancer cells suppressed cell proliferation and decreased the migration and invasion ability." (PMID 32824461, 2020).
lung carcinoma (continued). "On the contrary, increased expression of IQGAP3 was observed in all of these lung cancer subtypes." (PMID 29073199, 2017). "The OS of the lung cancer patients was less with increased IQGAP3 transcript level." (PMID 29073199, 2017). "Here we demonstrated that IQGAP3 is highly expressed in a large proportion of lung cancer samples." (PMID 24849319, 2014). "Moreover, we saw production of autoantibodies against IQGAP3 in a significant fraction of patients with IQGAP3-positive lung cancer." (PMID 24849319, 2014). "IQGAP3 is a key regulator of the Ras/ERK pathway and is highly expressed in various cancers, such as hepatocellular and lung cancers, in which it promotes tumor proliferation and invasion." (PMID 41446602, 2025). "Real-time RT-qPCR and IHC assays showed that IQGAP3 expression was increased in NSCLC cell lines and lung cancer tissues compared with normal lung cells and normal lung tissues, respectively." (PMID 35274003, 2022). "For example, IQGAP3 knockdown inhibited proliferation and ERK activity in cultured epithelial cells; IQGAP3 was also found to activate EGFR–ERK signaling and, thus, promote the metastasis of lung cancer cells." (PMID 33519444, 2020). "Among 25 pairs of lung cancer and adjacent non-cancerous tissues, 20 cancer tissues showed an increase in IQGAP3 mRNA." (PMID 24849319, 2014). "IQGAP3 was upregulated at mRNA level in 20 lung cancer tissues as compared to adjacent non-cancerous tissues in 25 paired samples by real-time PCR analysis." (PMID 24849319, 2014). "Additionally, higher IQGAP3 expression led to reduced FP and PPS in lung cancer patients." (PMID 29073199, 2017). "Upregulation of IQGAP3 expression was confirmed at the protein level by display of stronger immunohistochemical staining in cancer than in non-cancerous tissues in 80 out of 89 lung cancer samples." (PMID 24849319, 2014).
breast carcinoma (14 papers, 2014 to 2025). "This study shows IQGAP3 is overexpressed in breast cancer cell lines and tissues and is associated with the clinicopathological features of the disease." (PMID 33519444, 2020). "Univariate Cox regression analysis showed that the T category, N category, estrogen receptor (ER) status, progesterone receptor (PR) status, and IQGAP3 expression were significantly associated with survival in breast cancer patients." (PMID 33519444, 2020). "Protein expression of IQGAP3 was also evaluated immunohistochemically in archived paraffin-embedded specimens from 257 breast cancer patients, and the associations between IQGAP3 expression level, clinical characteristics, and prognosis were analyzed." (PMID 33519444, 2020). "We also analyzed the association of IQGAP3 protein expression with the survival outcomes and RT sensitivity in breast cancer patient cases." (PMID 33519444, 2020). "Association between IQGAP3 expression and clinicopathological features of breast cancer (n = 257)." (PMID 33519444, 2020). "Next, we investigated whether IQGAP3 overexpression levels in 257 cases of breast cancer specimens (detected via IHC) were associated with patients’ clinicopathological features." (PMID 33519444, 2020). "The top five tumor types that showed significant differences in IQGAP3 expression were breast cancer, lung adenocarcinoma, kidney renal clear cell carcinoma, lung squamous cell carcinoma, and liver hepatocellular carcinoma." (PMID 41446602, 2025). "According to a breast cancer study, kaempferol decreased the expression of IQGAP3 in breast cancer cells." (PMID 38731498, 2024). "In comparison to IQGAP2, IQGAP3 is highly expressed in breast cancer tissues relative to adjacent normal tissues." (PMID 36831467, 2023). "Numerous researchers have observed that IQGAP2 and IQGAP3 play antagonistic roles in gastric cancer, colorectal cancer, hepatocellular carcinoma, prostate cancer, ovarian cancer, breast cancer, and malignant lymphoma." (PMID 36831467, 2023). "Previously, IQGAP3 has been found to be highly expressed in breast cancer, colorectal cancer, gastric cancer, ovarian cancer, liver cancer, and pancreatic cancer." (PMID 36164370, 2022). "To examine the mechanism of IQGAP3 in the development of breast cancer radioresistance, we performed GSEA." (PMID 33519444, 2020). "Univariate and multivariate statistical analysis showed that IQGAP3 expression was an independent prognostic factor among all 257 breast cancer patients in our cohort (p = 0.003, p = 0.001)." (PMID 33519444, 2020). "Second, we lack direct evidence to support the role(s) of IQGAP3 in breast cancer progression and radioresistance." (PMID 33519444, 2020). "We explored the correlation between IQGAP3 expression profile and the clinicopathological features in breast cancer." (PMID 33519444, 2020). "We found IQGAP3 mRNA levels were increased in tumor samples compared with normal tissues by analyzing the publicly available microarray TCGA data for breast cancer." (PMID 33519444, 2020). "Higher IQGAP3 expression was also detected at the mRNA and protein level in breast cancer tissues compared to adjacent normal tissues from six different patients." (PMID 33519444, 2020). "We first analyzed the public microarray TCGA data of breast cancer and found IQGAP3 was overexpressed in radioresistant samples (n = 115) compared to radiosensitive samples (n = 600)." (PMID 33519444, 2020). "Regarding breast cancer, IQGAP3 knockdown inhibited cell proliferation and invasion in two breast carcinoma cell-lines." (PMID 33519444, 2020). "IQGAP3 was overexpressed in radioresistant breast cancer patients compared to radiosensitive patients." (PMID 33519444, 2020). "Together, this evidence suggests that IQGAP3 contributes to the development and progression of breast cancer." (PMID 33519444, 2020).
breast carcinoma (continued). "A significant change was observed in transcript levels of IQGAP2 and IQGAP3 in breast cancer compared to normal tissue, in different datasets of Oncomine." (PMID 29073199, 2017). "In agreement with our observations with in-silico analysis, a recent study has reported upregulation of protein levels of IQGAP3 in breast cancer and its role as an oncogene." (PMID 29073199, 2017). "In opposite to IQGAP2, the expression of IQGAP3 was increased from stage I to II in lung and breast cancer and, stage II to III in prostate and kidney cancer." (PMID 29073199, 2017). "Kaplan-Meier analysis showed that in breast cancer, higher levels of IQGAP3 expression and lower levels of IQGAP2 expression correlate with poor survival of the patient." (PMID 29073199, 2017). "Silencing IQGAP3 in breast cancer cells inhibits proliferation and metastasis." (PMID 38674130, 2024). "Additionally, upregulated IQGAP3 expression in individuals with breast cancer has been correlated with a highly unfavorable clinical outcome and increased radioresistance." (PMID 37370891, 2023). "The expression level of IQGAP3 in radiation resistant breast cancer was higher than that in radiosensitivity group, which may be related to DNA repair and PI3K-Akt-mTOR signal pathway." (PMID 36275458, 2022). "IQGAP3 has been shown to be overexpressed in liver cancer, colorectal cancer, and breast cancer." (PMID 36164370, 2022). "Therefore, we investigated the expression pattern of IQGAP3 in breast cancer cell lines compared to control cell lines, as well as in patient tissues and matched adjacent normal tissues." (PMID 33519444, 2020). "Moreover, silencing IQGAP3 was found to inhibit the proliferation, motility, and invasion of breast cancer cell lines." (PMID 33519444, 2020). "However, the correlation between IQGAP3 expression and prognosis or RT sensitivity in breast cancer remained unclear." (PMID 33519444, 2020). "Additionally, high levels of IQGAP3 expression were detected in 110/257 (42.8%) of archived paraffin-embedded breast cancer specimens." (PMID 33519444, 2020). "To confirm whether IQGAP3 is overexpressed in radioresistant breast cancer patients, we also examined IQGAP3 expression in 159 post-RT patients (radioresistant group n = 19; radiosensitive group n = 140) using IHC." (PMID 33519444, 2020). "Together, these results indicated IQGAP3 is overexpressed in breast cancer cell lines and tissues." (PMID 33519444, 2020). "Consistent with this study involving breast cancer cell lines, the present research provides evidence that IQGAP3 expression may have important clinical significance in breast cancer." (PMID 33519444, 2020). "In conclusion, IQGAP3 may be a reliable novel predictive biomarker of radioresistance and poor survival in breast cancer patients following RT." (PMID 33519444, 2020). "Moreover, our multivariate analysis confirmed IQGAP3 was an independent prognostic factor for RRFS in the subgroup analysis of radiosensitive breast cancer cases." (PMID 33519444, 2020). "Additionally, we found IQGAP3 expression was elevated at both the mRNA and protein level in all 12 breast cancer cell lines compared with the MCF-10A control cell line." (PMID 33519444, 2020). "An opposite trend was observed with IQGAP3 wherein poor OS of patients, more frequent relapses (low RFS) and metastatic events (low DMFS) were significantly associated with higher transcript levels of IQGAP3 in breast cancer patients." (PMID 29073199, 2017). "In IQGAP3, high gene amplification was observed in breast cancer (20.7% in Metabric and 11.9% in TCGA dataset), lung adenocarcinoma (12.6%) and liver cancer (12.3%), whereas in brain, lung squamous cell carcinoma, prostate, kidney and stomach cancer, the frequency of copy number change was very low." (PMID 29073199, 2017).